IGF1 (insulin like growth factor 1)
Diseases named in the same sentence as IGF1 in open-access papers (continued):
Sharing a sentence is not in itself a finding about the gene and the disease.
lung diseases (22 papers, 2008 to 2025). "Insulin-like growth factor-1 (IGF-1) appears to play an important role in lung disease, but circulating IGF-1 has been reported to be associated with a lower risk of airway hyperresponsiveness." (PMID 37242426, 2023). "Individuals with congenital IGF-1 signaling deficiencies are born predominantly with metabolic and systemic developmental alterations, less with lung disorders." (PMID 30018981, 2018). "By integrating bench-bed research methods, rational clinical diagnostic and therapeutic approaches concerning IGF-1 signaling might become applicable in lung disorders in the next few years." (PMID 30018981, 2018). "Elucidation of these questions by further bench-to-bedside researches may provide us with rational clinical diagnostic approaches and agents concerning IGF-1 signaling in lung diseases." (PMID 30018981, 2018). "Monocytes and macrophages are major targets and producers of IGF-1, which is implicated in cardiovascular, metabolic, and lung disease, but it is the IGF2R receptor transcript that is most strongly associated with the principal components of expression in both studies." (PMID 21217831, 2010). "In addition, current research indicates that IGF-1 is associated with lung disease." (PMID 32793225, 2020). "Two-sample Mendelian randomization (MR) analysis was then performed to assess the independent impact of IGF-1 exposure on these lung diseases." (PMID 36936149, 2023). "The main advantage is that the MR analysis can reduce the bias from residual confounding and reverse causality, thus strengthening the comprehensive assessment between circulating IGF-1 and pulmonary diseases." (PMID 36936149, 2023). "Mediators of the IGF1 signaling axis have been postulated as biomarkers for lung diseases, in various studies, since they are locally and/or systemically dysregulated." (PMID 34831169, 2021). "And the molecular-, time-, and organ-dependent and individualized IGF-1 signaling further obscures the potentials of its components for being candidate biomarkers for lung diseases." (PMID 30018981, 2018). "Insulin-like growth factor-1 (IGF-1) display a vital role in in the pathogenesis of lung diseases, however, the relationship between circulating IGF-1 and lung disease remains unclear." (PMID 36936149, 2023). "Third, epigenetic phenomena, such as methylation, and interactions between genes and environmental exposure may also influence IGF-1 in relation to lung diseases." (PMID 36936149, 2023). "The components of IGF-1 signaling pathways are potentiated as biomarkers as they are dysregulated locally or systemically in lung diseases, whereas data may be inconsistent or even paradoxical among different studies." (PMID 30018981, 2018). "In addition, temporal regulation and spatial localization of IGF-1 production may play an important role in the progression of lung disease." (PMID 36936149, 2023). "Moreover, IGF1 expression and/or signaling is upregulated in patients with idiopathic fibrotic lung diseases and could regulate myofibroblast activation and the epithelial to mesenchymal transition." (PMID 34831169, 2021). "Using multicolor immunohistochemistry, we demonstrated that protein expression levels of IGFBP2 as well as its selective ligands IGF1 and IGF2 were significantly downregulated in AEC2 cells of the lung disease groups compared with healthy controls." (PMID 40121473, 2025). "While the role of IGF-1 signaling and clinical relevance of serum IGF-1 level in lung disease have been studied, there are many unknowns." (PMID 39220366, 2024). "Furthermore, the administration of ghrelin does not significantly affect the IGF-1 level in healthy volunteers, patients with cardiovascular or pulmonary diseases, tumour-bearing animals, or our patients with CACS." (PMID 18182992, 2008).
autoimmune disease (21 papers, 2011 to 2025). A disorder resulting from loss of function or tissue destruction of an organ or multiple organs, arising from humoral or cellular immune responses of the individual to their own tissue constituents. "IGF-1 halts autoimmune disease progression in mouse models of type 1 diabetes (T1D) and multiple sclerosis (MS) in vivo." (PMID 41383600, 2025). "On the other side and in the context of autoimmune diseases such as systemic lupus erythematosus, IGF1 expression levels are inversely correlated with the number of specific immune cell types including NK cells." (PMID 38420122, 2024). "Previous studies have shown that IGF1 was involved in immune and autoimmune diseases, including Graves’ disease and RA, and plays an anti-inflammatory role in inflammatory responses." (PMID 37465678, 2023). "In autoimmune diseases, expression of IGF-1 is disturbed, resulting in low levels of IGF-1 on regulatory T cells (Treg), and thus an imbalance in active suppression of inflammation and immune responses has been observed." (PMID 33168080, 2020). "As an autoimmune disease, many inflammatory factors, such as insulin-like growth factor-1 (IGF-1), can be found in GO." (PMID 30671256, 2018). "Despite extensive study, the precise mechanism of IGF-1 action in countering autoimmune disease has remained obscure." (PMID 25339185, 2014). "By establishing Treg cells as a critical contributor to the therapeutic effects of systemic IGF-1 delivery in autoimmune disease, our report builds on previous studies documenting decreased Treg numbers and FoxP3 expression in the inflamed pancreas of autoimmune mice." (PMID 25339185, 2014). "While the specific role of GH/IGF-1 in autoimmune disease development is not fully understood, there is some evidence to suggest that GH may play a role in modulating immune function, which could potentially influence autoimmune disease development." (PMID 38892024, 2024). "However, to date, IGF-1-based therapies for selected autoimmune diseases have not been effective." (PMID 25339185, 2014).
inflammatory bowel disease (21 papers, 2013 to 2025). A spectrum of small and large bowel inflammatory diseases of unknown etiology. "We suggest that therapeutic decisions should consider the inflammatory features and local IGF‐1 levels assessed in colonic biopsies from patients suffering from inflammatory bowel disease or colitis‐associated cancer." (PMID 29907597, 2018). "Clinical data have recently implicated low IGF1 in flare-ups of inflammatory bowel disease, while basic studies have demonstrated that IGF1 directly inhibits pro-inflammatory cytokines in multiple animal cell types, inducing LPS-induced cytokine expression." (PMID 29869736, 2018). "However, chronic inflammation, often detected in situations like inflammatory bowel disease and juvenile idiopathic arthritis, can significantly disrupt the GH/IGF-1 axis, causing a relevant growth impairment." (PMID 40310145, 2025). "Research indicates an inverse correlation between serum IGF-1 levels and the severity of several autoimmune diseases, including rheumatoid arthritis and inflammatory bowel disease (IBD)." (PMID 40496563, 2025). "In accordance with our results, previous studies found endogenous IGF-1 and IGFBP-3 levels negatively associated with the degree of inflammation both in HSCT settings and in patients with inflammatory bowel disease." (PMID 32793242, 2020). "The IGF-1/IGFBP-3 complex has been shown to exert anti-apoptotic effects on small intestinal epithelial cells, and lower IGFBP-3 levels have been associated with disease activity in inflammatory bowel disease." (PMID 40724799, 2025).
Central hypothyroidism (20 papers, 2010 to 2026). A type of hypothyroidism due to an insufficient stimulation of an otherwise normal thyroid gland. "Endocrine evaluation confirmed severe panhypopituitarism, including central adrenal insufficiency, central hypothyroidism, central hypogonadism, and severe growth hormone deficiency (IGF-1 Z-score -2.7)." (PMID 42232758, 2026). "A detailed review of her obstetric history, combined with endocrine testing showing central hypothyroidism, adrenal insufficiency, and low IGF-1, led to the correct diagnosis." (PMID 41783865, 2026). "On the basis of this profile, a diagnosis of PSIS with multiple pituitary hormone deficiency (GHD due to low insulin-like growth factor-1 (IGF-1), central hypothyroidism due to low free T4 and normal TSH, and adrenal insufficiency due to low ACTH) was made." (PMID 40539145, 2025). "After surgery, central hypogonadism was detected in 40.8% of patients (30% of which were postmenopausal women), central hypothyroidism in 29.3%, central adrenal insufficiency in 27.4% (22.7% with the strict analysis), and low IGF-1 in 17% of patients." (PMID 37222882, 2023). "Before surgery, central hypogonadism was detected in 62.4% of patients (31.5% of which were postmenopausal women), central hypothyroidism in 41%, central adrenal insufficiency in 30.8% (21.3% with the strict analysis), and low IGF-1 in 29.9% of patients." (PMID 37222882, 2023). "In patients with central hypothyroidism, it is recommended, at the diagnosis, to perform the following tests: morning cortisol and ACTH, LH, FSH, prolactin, IGF-1, testosterone in males, estradiol in females and MRI of the hypothalamus-pituitary region, unless contraindicated." (PMID 35407442, 2022). "Nonetheless, central hypothyroidism and GH deficiency did not resolve (TSH 0.08 mU/L, freeT4 0.83 ng/dl, IGF1 25 ng/ml)." (PMID 25260871, 2014).
diabetic neuropathy (20 papers, 2011 to 2026). A chronic, pathological complication associated with diabetes mellitus, where nerve damages are incurred due to diabetic microvascular injury involving small blood vessels that supply these nerves, resulting in peripheral and/or autonomic nerve dysfunction. "The expressions of IGF-1 and IGF-1R were dysregulated in diabetic patients and considered to be associated with the defects of peripheral nerve myelination in diabetic neuropathy." (PMID 40420926, 2025). "Several studies have demonstrated improvements in behavioral signs of diabetic neuropathy after IGF-1 treatment." (PMID 37242543, 2023). "All these data indicated that spinal IGF-1/IGF1R signaling downregulated parallel to the development of painful diabetic neuropathy (PDN)." (PMID 35401920, 2022). "We previously demonstrated the beneficial consequence of insulin and IGF-1 treatment in preventing diabetic neuropathy in STZ-induced diabetic rats." (PMID 35298717, 2022). "We therefore used in vitro cell culture systems and animal models of diabetic neuropathy to characterize endogenous IGF-1 in sensory neurons and determine the factors regulating IGF-1 expression and/or affecting neuronal health." (PMID 35298717, 2022). "Viral delivery of IGF1 to models of diabetic neuropathy also revealed positive actions of IGF1 perhaps through vascular endothelial growth factor expression (VEGF), and signaling via Akt/PI3K pathways in sensory and motor nerves." (PMID 28066166, 2016). "In experimental diabetic neuropathy, treatment with IGF-1 reversed neuronal hyperactivity in the spinal cord and in the periaqueductal gray matter and prevented behavioral signs of pain." (PMID 22776095, 2012). "In the present study we focused on IGF-1 in pancreatic islet β-cells, since IGF-1 activity also is intimately related to development of diabetic neuropathy." (PMID 22194889, 2011). "The pathology of diabetic neuropathy involves oxidative stress on pancreatic β-cells, and is related to decreased levels of Insulin-like growth factor 1 (IGF-1)." (PMID 22194889, 2011). "Upregulation of IGF-1 has also been shown to protect Schwann cells from glucose-induced apoptosis, both in purified Schwann cells in vitro and within a streptozotocin-treated diabetic rat model, suggesting a therapeutic potential of IGF-1 in diabetic neuropathy." (PMID 40612106, 2025). "In addition, painful diabetic neuropathy significantly reduces the expression of IGF-1 in spinal cord." (PMID 37497005, 2023). "Furthermore, pre-diabetic mice maintained on a high-fat high-sugar Western diet for 14 weeks exhibiting diabetic neuropathy displayed a 3.7-fold decrease in IGF-1 transcripts in DRG (q value = 0.000019)." (PMID 35298717, 2022). "Furthermore, overexpression of IGF-binding protein 5 (an intrinsic IGF-1 inhibitor) or depletion of IGF1R promoted a neurodegeneration phenotype in mice that resembled the nerve damage observed in humans with diabetic neuropathy." (PMID 35298717, 2022). "In particular, IGF-1 is known to be decreased in serum of rats with diabetic neuropathy." (PMID 22194889, 2011). "Great interest has been generated by the role of nerve growth factors in the pathogenesis of DAN: for instance, insulin-like growth factor-1 (IGF-1) and neurotrophin-3 (NT-3) have been demonstrated to reverse experimental diabetic neuropathy." (PMID 25520703, 2014). "Decreased serum IGF-1 level and IGF-1 mRNA expression are shown in experimental diabetic rats, and administration of IGF-1 results in improvement of diabetic neuropathy." (PMID 22927874, 2012). "We have previously shown that insulin-like growth factor-1 (IGF-1) improves mitochondrial oxygen consumption rate (OCR) through activation of AMP-activated protein kinase (AMPK) and protects against nerve degeneration in experimental diabetic neuropathy." (PMID 33592336, 2021).
diabetic neuropathy (continued). "A recent study of motor axonopathy induced in mice by overexpression of an inhibitory binding protein for IGF-1, led to the suggestion that a defect in well-known neurotrophic and myotrophic effects of IGF-1 might be common to both diabetic neuropathy and ALS." (PMID 28798720, 2017). "Our data support the idea that IGF-1–LNP may provide a path to safe and effective gene therapy in neurodegenerative disorders, while the CEBPβ and NFAT1 transcription factors could also represent promising targets manipulating endogenous IGF-1 production for the treatment of diabetic neuropathy." (PMID 35298717, 2022).
hypogonadotropic hypogonadism (20 papers, 2014 to 2026). Abnormal ovarian or testicular function due to insufficient hormonal stimulation from the hypothalamic-pituitary axis. "In laboratory tests, the most common manifestation is ACTH and thyrotropin (TSH) deficiency, followed by hypogonadotropic hypogonadism and growth hormone (GH) and insulin-like growth factor-1 (IGF1) deficiency." (PMID 32824462, 2020). "At the presentation in both patients hypogonadotropic hypogonadism was associated with low IGF1 and low freeT4 levels associated with mildly elevated TSH levels." (PMID 25260871, 2014). "At 48–72 h, we received the remaining results of the blood test requested by endocrinology after the first evaluation, updating the diagnosis to “panhypopituitarism” after documenting hypogonadotropic hypogonadism and both insulin-like growth factor 1 (IGF-I) and prolactin deficiencies (Column 3)." (PMID 39444496, 2024). "Therefore, hypogonadotropic hypogonadism, low IGF-1 levels, and weight loss may contribute to low PBM in patients with AN." (PMID 41030740, 2025). "Additional findings include hypogonadotropic hypogonadism and low levels of insulin-like growth factor-1 (IGF-1)." (PMID 39941803, 2025). "High GH and IGF-1 disrupt the typical pulsatile secretion of gonadotropins at the hypothalamic–pituitary level, leading to hypogonadotropic hypogonadism." (PMID 39337013, 2024). "The evaluation of other anterior pituitary function showed that they all had hypogonadotropic hypogonadism, and 2 of them had decreased insulin like growth factor 1 (IGF1)." (PMID 38093965, 2023). "Low IGF-1 levels due to GH resistance, low sex hormone levels due to functional hypogonadotropic hypogonadism, elevated cortisol and low leptin levels all contribute to low bone mass observed in patients with AN." (PMID 32219087, 2020). "Evaluation showed hypogonadotropic hypogonadism and low IGF-1." (PMID 27656301, 2016). "In the presence of (secondary) hypogonadotropic hypogonadism, it is recommended to check the remaining hormonal axes (Prolactin, Cortisol and ACTH in the morning, FT4, TSH, IGF-1) and a pituitary MRI with contrast medium (unless contraindicated)." (PMID 35407442, 2022). "Evaluation showed hypogonadotropic hypogonadism (E2 17 pg/mL, LH 0.7, and FSH 1.2 mIU/mL) and IGF-1 34 ng/dL (SDS −3.2) consistent with growth hormone deficiency." (PMID 27656301, 2016). "In the presence of hypogonadotropic hypogonadism, it is recommended to carry out a pituitary MRI with a contrast agent (unless contraindicated), and to check the remaining hormonal axes with morning cortisol and ACTH, TSH, FT4, prolactin, and IGF-1 assays." (PMID 35407442, 2022).
muscle atrophy (20 papers, 2012 to 2025). The loss of muscle tissue due to inactivity or disease. "ANGII-induced muscle atrophy is associated with reduced local and systemic insulin-like growth factor 1 (IGF-1) and insulin-like growth factor binding protein 3 (IGFBP3) levels." (PMID 38616362, 2024). "The role and relative importance of IGF-1 signaling likely differs between muscle atrophy models, and further studies are required to develop effective strategies to apply IGF-1 to treat muscle atrophy in human patients." (PMID 32858949, 2020). "The suppression of the IGF-1/Akt/PKB pathway and induction of atrophy-specific E3 ubiquitin ligases, such as Atrogin-1 and MUSA1, further support the link between creatine deficiency and muscle atrophy." (PMID 39952955, 2025). "Therefore, despite several reports indicating that STCs play a role in growth, its contribution by modulating the bio-disponibility of local IGF-1 during muscle atrophy remains to be established." (PMID 37762414, 2023). "In conclusion, miR-29b contributes to multiple types of muscle atrophy via targeting of IGF-1 and PI3K(p85α), and that suppression of miR-29b may represent a therapeutic approach for muscle atrophy induced by different stimuli." (PMID 28541289, 2017). "Furthermore, CRISPR-SAM was employed to stimulate the expression of multiple IGF1 gene isoforms in human and mouse myoblasts in vitro, which facilitated myogenic differentiation and may prove beneficial for muscle atrophy therapy." (PMID 40650152, 2025). "Indeed, our study disclosed a similar dysfunction of the IGF-1 system in another compartment of sALS patients that could play an important role in both MN degeneration and muscle atrophy." (PMID 22246875, 2012). "In addition, future studies should be carried out in patients with muscle atrophy to analyze whether there is a correlation between IGF-1, other pro-hypertrophic markers, BDNF levels, an increase in muscle circumference, and an improvement in the subjects’ mood or cognitive processes." (PMID 39329748, 2024). "It has been reported that the IGF-1/PI3K/Akt signaling pathway reduces denervation-, unloading-, and joint immobilization-induced muscle atrophy, and that the injection or overexpression of IGF-1 counteracts denervation- and age-related muscle atrophy." (PMID 36505042, 2022). "Importantly, we found that IGF-1, PI3K(p85α) and the downstream (from IGF-1) effectors were all decreased in the in vitro muscle atrophy models and miR-29b agomir could decrease them in vivo, providing some insights of their potential roles in muscle atrophy in vivo." (PMID 28541289, 2017). "Muscle atrophy was triggered by the PBM-based diet, but this effect was improved with FPHs supplementation, as demonstrated by a significant increase in muscle fiber quantification (fiber density, hyperplasia, and hypertrophy) and muscle health relevant gene expression (IGF-1, myf5, and MyoG)." (PMID 37057066, 2023). "Importantly, co-treatment with CB appears to antagonize the DEX-induced inhibitory effect on IGF1 expression, and this may account in part for the inhibition of DEX-induced muscle atrophy in the CB+DEX group." (PMID 26053620, 2015). "Thus, our results suggest that IGF-1 may balance the degradation of proteins involved in contraction through its specific action on MuRF1, without impeding a generalized muscle atrophy." (PMID 23755187, 2014).